MTOR (mechanistic target of rapamycin kinase)
Diseases named in the same sentence as MTOR in open-access papers (continued):
Sharing a sentence is not in itself a finding about the gene and the disease.
rhabdomyoma (9 papers, 2020 to 2025). A benign mesenchymal tumor arising from skeletal or cardiac muscle. "Tuberous sclerosis complex (TSC), caused by autosomal dominant mutations in either TSC1 or TSC2 that causes a plethora of cellular dysfunctions due to mTOR inhibition, has heart symptoms in the form of rhabdomyomas in addition to other organ involvements such as the skin and brain." (PMID 39241028, 2024). "Studies were included if they reported on pregnancies with fetal cardiac tumor and rhabdomyoma entity suspicion treated with mTOR inhibitors." (PMID 40933704, 2025). "Only one newborn received immediate postnatal therapy with an mTOR inhibitor, specifically everolimus, due to its positive effects on the size of the known rhabdomyoma." (PMID 39518472, 2024). "Keywords included “mTOR Inhibitor”, “Rapamycin”, “tuberous sclerosis complex”, “prenatal”, and “rhabdomyoma”." (PMID 39518472, 2024). "The ability of mTOR inhibitors to reduce rhabdomyoma size after birth is well established, as demonstrated in numerous case series." (PMID 39518472, 2024). "However, a recent study, showed that postnatal treatment with the mTOR inhibitor everolimus initiated significant regression of a prenatally diagnosed giant rhabdomyoma of the hearth suggesting a role for mTOR inhibitors in early onset rhabdomyomas." (PMID 36982349, 2023). "The use of mTOR inhibitors was evaluated in pediatric patients for the treatment of rhabdomyoma." (PMID 36982349, 2023). "Prenatal diagnosis has gained interest with recent data suggesting that maternal treatment with inhibitors of the mTOR pathway (everolimus and sirolimus) may be beneficial for rhabdomyomas without any serious adverse events reported." (PMID 32973442, 2020).
seminoma (9 papers, 2018 to 2025). A radiosensitive malignant germ cell tumor found in the testis (especially undescended), and extragonadal sites (anterior mediastinum and pineal gland). "Due to the loss or reduced expression of LKB1 in seminoma samples, we decided to investigate if suppression of mTOR signaling in seminoma cells will affect their growth." (PMID 36969070, 2023). "These suggest involvement within the KIT/RAS/MAPK and PI3K/AKT/mTOR (PAM) pathways for seminoma development." (PMID 41154418, 2025). "The pattern of alterations observed suggests involvement of the KIT/RAS/MAPK and PI3K/AKT/mTOR (PAM) signaling pathways in seminoma development." (PMID 41154418, 2025). "In summary, analysis of AACR Project GENIE data sheds light on a distinct seminoma genomic profile characterized by recurrent mutations in KIT, KRAS, and MTOR, as well as focal copy number alterations in CDKN1B, KRAS, CCND2, and H3F3C." (PMID 41154418, 2025). "In this study, we showed downregulation of LKB1 expression in seminoma patients and suppression of the mTOR pathway in a seminoma cell line resulted in reduced cell viability and proliferation." (PMID 36969070, 2023). "With the use of a seminoma cell line (TCam-2), we showed that suppression of the mTOR pathway results in reduced viability and proliferation of cancer germ cells." (PMID 36969070, 2023). "First, we confirmed that mTOR signaling is upregulated in seminoma by examining the expression of mTOR and p4EBP1." (PMID 36969070, 2023). "A 3D culture model of human seminoma was developed from TCam-2 cells, and two mTOR inhibitors were tested for their efficacy against these cancer cells." (PMID 36969070, 2023). "TDRG1 peptide action in seminoma mainly relies on the activation of PI3K/Akt/mTOR oncogenic signaling pathway, since it is able to positively regulate the expression levels of p-PI3K, p-Akt, and p-mTOR, as well as to affect the translocation of nuclear p-Akt." (PMID 33767982, 2021). "It positively regulated the p-mTOR and affected the cell cycle progression in seminoma cells during CDDP treatment." (PMID 37303943, 2021). "TDRG1 regulated the CDDP sensitivity through the PI3K/AKT/mTOR signaling and intrinsic apoptosis pathway in seminoma cells." (PMID 37303943, 2021). "Association was also identified for RAS/RAF with seminoma and extragonadal disease (p = 2.9 × 10−8 and p = 4.7 × 10−6, respectively) and PI3K/MTOR pathway with seminoma (p = 0.02)." (PMID 32366847, 2020). "Similar pathways were present in non-seminomas as well, with miRNAs and mRNA fragments showing cancer related pathways, with mTOR, MAPK, ERBb2, and PI3K-Akt showing highest significance." (PMID 33251139, 2020). "In seminomas the expressed miRNAs and mRNA fragments also showed the cancer related pathways mTOR, MAPK and AMPK as well as the proteoglycans in cancer pathway." (PMID 33251139, 2020). "Down-regulated expression of TDRG1 reduced the biological activity of TGCT cells, and enhanced proliferation and migration of seminoma cells through modulation of the PI3 K/Akt/mTOR signaling pathway and mitochondria-mediated apoptotic pathway." (PMID 31164797, 2019). "Remarkably, lncRNA TDRG1 was described to activate the same pathway in endometrial carcinoma and osteosarcoma, thereby one could argue that PI3K/Akt/mTOR pathway activation in seminoma is also ascribable to this lncRNA." (PMID 33767982, 2021). "The role of TDRG1 in tumorigenesis and the progression of seminoma, as well as its role in regulating chemosensitivity of seminoma to cisplatin through the PI3K/Akt/mTOR signaling pathway, has been previously defined." (PMID 30430771, 2018).
seminoma (continued). "Through adjusted analysis, we delineate independent association with seminoma histology for mutations in KIT, KRAS, NRAS and Pi3K/MTOR pathway gene sets and, independent of histology, association of KIT mutation with platinum sensitivity." (PMID 32366847, 2020).
silicosis (9 papers, 2021 to 2025). Silicosis is a respiratory disease caused by breathing in (inhaling) silica dust. "Serum/lung tissue L-Trp is lower in PF mice than in silicosis mice; exogenous L-Trp activates mTOR/S6- to promote EMT and fibroblast activation, aggravating fibrosis." (PMID 41395479, 2025). "PPI analysis identified the PI3K/AKT/mTOR signaling axis as the most prominently involved pathway in HHT's anti-fibrotic effects in silicosis, consistent with the findings from KEGG analysis." (PMID 40396273, 2025). "Our findings showed that miR-29a-3p promotes autophagy via the Akt3-mediated mTOR signaling pathway to suppress PF, revealing a possible therapeutic target for the treatment of silicosis." (PMID 37511199, 2023). "IHC and Western blot results showed that Akt3 levels were evidently elevated in the lung tissues of mice with silicosis compared to those in the control group mice, and phospho-mTOR protein levels were also increased." (PMID 37511199, 2023). "We first examined the expression of Akt3 and phospho-mTOR in a mouse model of silicosis." (PMID 37511199, 2023). "We speculate that glycyrrhizic acid inhibits the interaction between HMGB1 and BRG1 through the PI3K/Akt/mTOR pathway to affect the progression of silicosis." (PMID 35886594, 2022). "Therefore, the development of natural or synthetic drugs targeting mTOR may be a promising method for silicosis treatment in clinical settings." (PMID 34360876, 2021). "HMGB1 and BRG1 are also highly expressed in the mouse silicosis model, and glycyrrhizic acid can inhibit the expression of HMGB1/BRG1 through the PI3K/Akt/mTOR pathway." (PMID 35886594, 2022). "Glycyrrhizic acid can affect the BRG1 and PI3K/Akt/mTOR pathway by inhibiting the expression of HMGB1 and delay the progression of silicosis in mice." (PMID 35886594, 2022). "Collectively, the current study demonstrates that HHT shows significant potential as a therapeutic agent for silicosis by targeting CCR1 and the PI3K/AKT/mTOR signaling pathway, highlighting it as a promising candidate for clinical translation for silicosis treatment." (PMID 40396273, 2025). "To explore the possible role of AMPK in silicosis, we investigated the expression of AMPK and mTOR." (PMID 34434111, 2021). "LPS further intensifies the blockade of AM autophagic degradation of silicosis patients via the activation of toll-like receptor 4 (TLR4)/myeloid differentiation factor 88 (MyD88) and the toll-like receptor adaptor molecule 1 (TLRAM1) signaling pathway or inhibition of mTOR signaling pathway." (PMID 34360876, 2021).
Splenomegaly (9 papers, 2016 to 2024). Abnormal increased size of the spleen. "Moreover, lysosomal dysfunction causes mechanistic target of rapamycin (mTOR) overexpression in those cells; interestingly, mTOR inhibition led to a rescue in macrophage dysfunction and peripheral immunity perturbation, including splenomegaly and lymphadenopathy." (PMID 34025358, 2021). "Other studies also showed that splenomegaly was associated with splenic fibrosis in rats with PPVL31 and that mTOR signaling promoted splenomegaly in these rats." (PMID 30573742, 2018). "They reported that rapamycin-induced mTOR inhibition significantly decreased splenomegaly through the inhibition of lymphocyte proliferation, angiogenesis, fibrogenesis and tissue inflammation levels, which ultimately led to a decrease in portal pressure." (PMID 28535799, 2017). "This study also systematically determined the role of mTOR signaling pathway during the development of splenomegaly and identified the possible target for therapeutic intervention." (PMID 26734934, 2016). "Intriguingly, splenomegaly developed time-dependently in portal hypertensive rat that accompanied with progressive activation of mTOR signaling pathway." (PMID 26734934, 2016). "Rapamycin or vehicle was administered to rats to determine the contribution of mTOR signaling pathway in the development of splenomegaly." (PMID 26734934, 2016). "To further identify the relationship between mTOR signaling pathway and pathophysiology of splenomegaly, we determined the effects of mTOR blockade on pathophysiology of splenomegaly." (PMID 26734934, 2016). "mTOR blockade by rapamycin profoundly ameliorated splenomegaly by limiting lymphocytes proliferation, angiogenesis, fibrogenesis and inflammation as well as decreasing portal pressure." (PMID 26734934, 2016). "On the other hand, loss of mTOR function via ablation of the mTORC1 component Raptor (regulatory-associated protein of mTOR) in mouse HSCs leads to non-lethal pancytopenia, splenomegaly, and accumulation of monocytoid cells." (PMID 35663405, 2022). "Collectively, these results support the notion that activation of mTOR signaling pathway may be one of the pathogenetic mechanisms leading to splenomegaly, and mTOR blockade by rapamycin can effectively ameliorate splenomegaly." (PMID 26734934, 2016). "mTOR blockade by rapamycin could profoundly ameliorate splenomegaly by limiting lymphocytes proliferation, angiogenesis, fibrogenesis and inflammation as well as decreasing portal pressure in portal hypertensive rats." (PMID 26734934, 2016). "Consistently, these reverse effects were also observed in splenomegaly in our experiments, which indicated that mTOR signaling pathway might be systematically activated in portal hypertension syndrome, and rapamycin could be a promising agent in reversing portal hypertension syndrome." (PMID 26734934, 2016). "Combining the findings reported here and in our previous publication, targeting mTOR signaling could represent a potentially effective therapeutic approach for PHT, ameliorating not only intrahepatic disturbances, but also splenomegaly." (PMID 26734934, 2016).
ulcer (9 papers, 2015 to 2025). "Furthermore, since uniformly strong mTOR expression was observed in all APS-associated ulcer samples, it is unlikely that disease severity—at least in the case of clinically established ulcers—would have an effect on the magnitude of mTOR expression." (PMID 40141392, 2025). "In contrast, our present findings indicate that in non-APS-associated ulcers, despite the presence of significant inflammation and hyperproliferation, the mTOR pathway is not activated." (PMID 40141392, 2025). "A transient pharmacological activation of the PI3K-Akt-mTOR signaling axis has been considered a novel clinical intervention strategy to accelerate wound (ulcer) healing, and we recently demonstrated that the pro-healing effect of a mutated form of rhNGF includes Akt regulation." (PMID 35386010, 2022). "The collective evidence involving the mechanisms of mTOR inhibitors and the lessons learned at the clinical and research levels for recurrent aphthous ulceration may provide important context for new research directed to mIAS pathobiology." (PMID 27334013, 2016). "Insights into the mechanism of action of mTOR inhibitors and naturally occurring oral mucosal lesions such as recurrent aphthous ulceration may thus be valuable in informing future research directions involving mIAS." (PMID 27334013, 2016). "Alternatively, specific components (e.g., cytokines) of the inflammatory/proliferative pathways required to activate mTOR signaling could be present in APS-associated ulcers but are apparently absent in classical leg ulcers." (PMID 40141392, 2025). "Thus, MEBT/MEBO participates in ulcer wound repair and healing via regulating the PI3K–Akt–mTOR signalling pathway." (PMID 31967912, 2020).
adrenocortical carcinoma (8 papers, 2012 to 2024). "This seems particularly relevant in light of the recent finding that mTOR pathway is activated and involved in growth stimulation of paediatric adrenocortical carcinomas, tumour entities that are also associated with IGF2 overexpression." (PMID 22952916, 2012). "Several studies have shown the involvement of IGF1/IGF1R and mTOR pathways in the pathogenesis of adrenocortical carcinoma." (PMID 29507530, 2018). "The IGF and mTOR-pathways are considered as potential targets for therapy in patients with adrenocortical carcinoma (ACC)." (PMID 30838516, 2019). "A decrease of p-AKT and p-mTOR was demonstrated by the used N-terminal HSP90 inhibitors, luminespib and ganetespib, in both adrenocortical carcinoma cell lines." (PMID 31379752, 2019). "Using mTOR inhibitors could weaken the promoting effect of IGF on the proliferation and viability of tumor cells, while combining IGF2 inhibitors could provide a better curative effect on patients with adrenocortical carcinoma." (PMID 33582655, 2021).
AIDS (8 papers, 2008 to 2025). A syndrome resulting from the acquired deficiency of cellular immunity caused by the human immunodeficiency virus (HIV). "Another mTOR inhibitor, everolimus, has shown great potential in the treatment of various AIDs by precisely inhibiting the mTOR signaling pathway, regulating cell growth and proliferation, and thus influencing the immune response." (PMID 39575238, 2024). "At least three kinases of the phosphatidylinositol 3-kinase family, namely ATM, mTOR and DNA-dependent protein kinase (DNA-PK), operate at two different levels of AIDS pathogenesis." (PMID 18560558, 2008). "Among the most promising targeted therapies, Rapamycin, an mTOR inhibitor that targets the KS paracrine oncogenesis axis and the multi-kinase inhibitor Imatinib which targets PDGFRA, c-kit and c-abl showed some responses in transplant and AIDS-KS respectively." (PMID 33057440, 2020). "Previous results in non-HIV/AIDS populations have demonstrated that DLBCL patients with active mTOR pathway have a trend toward shorter OS when compared to patients with mTOR negative tumors." (PMID 28192480, 2017). "In patients with HIV/AIDS, this would include appropriate ART while in post-organ transplant patients this would entail a reduction of immunosuppressive therapy, with certain studies suggesting that switching of immunosuppressive therapy to mTOR inhibitors such as sirolimus improves outcome." (PMID 39781121, 2024).
Angiofibroma (8 papers, 2014 to 2024). A benign neoplasm of fibrous tissue in which there are numerous small and large, frequently dilated, vascular channels. "We studied immunoexpressions of phosphorylated (p-) mTOR effectors in fibrous papules, TSC-associated angiofibromas, and normal skin controls." (PMID 24558502, 2014). "Angiofibromas in TSC were coincidentally found to respond favourably to the mTOR inhibitor rapamycin." (PMID 24910976, 2014). "A germline mutation of the TSC1 or TSC2 gene, leading to activation of the mammalian target of rapamycin (mTOR) pathway, accounts for the pathogenesis of TSC-associated angiofibromas." (PMID 24558502, 2014). "The study identified amongst 11 dermatological conditions that over 157 of the 262 patients frequently had mostly angiofibromas linked to TSC, and that topically applied mTOR inhibitors, such as sirolimus was more effective against angiofibromas than placebo and were well tolerated." (PMID 31370278, 2019). "Rapamycin, a mTOR inhibitor, is effective in treating TSC-associated angiofibromas." (PMID 24558502, 2014). "By incorporating adjunct interventions such as topical sirolimus or other targeted agents that modulate the mTOR pathway or integrating multimodal treatments targeting different aspects of angiofibroma pathogenesis, treatment outcomes may be enhanced synergistically." (PMID 39034975, 2024). "Our trial data support this assertion and we suggest that mTOR does not play an active role in the maintenance or growth of fibrofolliculomas, in contrast to angiofibromas in TSC." (PMID 24910976, 2014).
Ataxia (8 papers, 2018 to 2025). Ataxia refers to impaired coordination of voluntary muscle movement. "Family with sequence similarity 201-member A (FAM201A) was reported to mediate the radiosensitivity of ESCC by regulating ataxia telangiectasia mutation and mammalian target of rapamycin (mTOR) expression via miR-101." (PMID 31391206, 2019). "Identification of putative ATR (Ataxia telangiectasia and Rad3 related), ATM (Ataxia telangiectasia mutated), mTOR (mechanistic Target of Rapamycin) and DNA-PKcs (DNA-dependent protein kinase, catalytic subunit) Leishmania major protein sequences." (PMID 30265735, 2018). "Sphingolipid signaling pathway and sphingolipid metabolism are also found in the same cluster with Ras signaling and mTOR signaling pathways in fibroblast “ataxia” datasets, which are directly associated with Rap1 signaling and autophagy based on KEGG reference pathway-to-pathway network." (PMID 32937819, 2020). "Spinocerebellar ataxia, pyruvate metabolism, mTOR signaling pathway, mitophagy animal, and HIF-1 signaling pathway were significantly up-regulated." (PMID 33859672, 2021). "Thus, in the patients where we have previously shown a decrease in pS6 and thus mTOR signaling, defects in establishment of proper circuitry could occur and result in ataxia even in the absence of obvious cerebellar atrophy." (PMID 36219306, 2023).